VIPR1 (vasoactive intestinal peptide receptor 1)
Description:
G protein-coupled receptor activated by the neuropeptides vasoactive intestinal peptide (VIP) and pituitary adenylate cyclase-activating polypeptide (ADCYAP1/PACAP). Binds VIP and both PACAP27 and PACAP38 bioactive peptides with the following order of ligand affinity VIP = PACAP27 > PACAP38. Ligand binding causes a conformation change that triggers signaling via guanine nucleotide-binding proteins (G proteins) and modulates the activity of downstream effectors. Activates cAMP-dependent pathway.
Synonyms: VIP-R-1; PACAP-R-2; PACAP-R2; VPAC1R; VPAC1; RDC1; HVR1; II; V1RG; VAPC1; VIPR; VIRG; VPCAP1R
Tractability: Small molecule: a structure with a bound ligand is known. Antibody: UniProt places it where antibodies can reach, with high confidence; its Gene Ontology location is reachable by antibodies, with high confidence; UniProt predicts a signal peptide or a membrane-spanning region. PROTAC: a small molecule that binds it is known.
Target class: Peptide receptor (family B GPCR); Vasoactive intestinal peptide receptor; Membrane receptor; Family B G protein-coupled receptor
Safety:
Unwanted effects reported when the protein is acted on. In parentheses: how it was acted on, where the effect was seen, and who reports it.
decreased gastrointestinal transit (activation, acute dosing; immune, gastrointestinal; source: Lynch et al. (2017))
decreased inflammation (activation, acute dosing; immune, gastrointestinal; source: Lynch et al. (2017))
immunosuppression (activation, acute dosing; immune, gastrointestinal; source: Lynch et al. (2017))
increased gastrointestinal transit (inhibition, acute dosing; immune, gastrointestinal; source: Lynch et al. (2017))
inflammation (inhibition, acute dosing; immune, gastrointestinal; source: Lynch et al. (2017))
Gene: Protein-coding gene on chromosome 3 (42,489,299 to 42,537,688, forward strand). Ensembl gene ENSG00000114812.
Subcellular location: Cell membrane
Pathways (Reactome):
Signal Transduction: G alpha (s) signalling events; Glucagon-type ligand receptors
Gene Ontology:
Molecular function: peptide hormone binding; pituitary adenylate cyclase-activating polypeptide receptor activity; protein binding; vasoactive intestinal polypeptide receptor activity; G protein-coupled peptide receptor activity; G protein-coupled receptor activity; transmembrane signaling receptor activity
Biological process: adenylate cyclase-activating G protein-coupled receptor signaling pathway; G protein-coupled receptor signaling pathway, coupled to cyclic nucleotide second messenger; adenylate cyclase-modulating G protein-coupled receptor signaling pathway; G protein-coupled receptor signaling pathway; positive regulation of cell population proliferation; cell surface receptor signaling pathway
Cellular component: receptor complex; plasma membrane; membrane
Genetic constraint (gnomAD): Loss-of-function variants: 63 observed, 58.18 expected, observed/expected ratio (o/e) 1.08, 90% interval 0.88 to 1.34. The upper end of that interval is the gene's LOEUF score, 1.34, which puts it in group 5 of 6, group 1 being the genes least tolerant of losing a copy. Missense variants: 626 observed, 583.94 expected, observed/expected ratio (o/e) 1.07, 90% interval 1 to 1.14. Synonymous variants: 251 observed, 232.94 expected, observed/expected ratio (o/e) 1.08, 90% interval 0.97 to 1.2.
Homologues: Orthologues: chimpanzee VIPR1 (99% identical), macaque VIPR1 (98% identical), rabbit VIPR1 (93% identical), pig VIPR1 (88% identical), mouse Vipr1 (85% identical), rat Vipr1 (84% identical), dog VIPR1 (84% identical), guinea pig VIPR1 (78% identical), tropical clawed frog vipr1 (61% identical), zebrafish vipr1b (55% identical). Paralogues in human: ADCYAP1R1 (48% identical), SCTR (46% identical), VIPR2 (46% identical), GHRHR (40% identical), PTH1R (38% identical), PTH2R (38% identical), GLP1R (36% identical), GCGR (35% identical), GIPR (35% identical), GLP2R (34% identical), CALCR (28% identical), CALCRL (28% identical), and 30 more.